INS (insulin)
Diseases named in the same sentence as INS in open-access papers (continued):
Sharing a sentence is not in itself a finding about the gene and the disease.
Hyperglycemia (continued). "Indeed, insulin, at a dose not affecting the hyperglycemia, has been shown to improve neuropathy and relief hyperalgesia." (PMID 24279796, 2013). "Present finding of hyperglycemia after chronic regular cola drinking may be consistent with such possibility, i.e: reduced beta cell mass and insulin secretion which have not been evaluated in this study." (PMID 23547749, 2013). "Nevertheless, there are many variations in the injection protocol in terms of dosage, route of injection, and with or without insulin compensation that are usually based on the practice in individual laboratories; nonetheless, all mice end up with hyperglycemia in 1 to 4 weeks after STZ injection." (PMID 24286086, 2013). "This should be interpreted with caution, and may be a consequence of insufficient insulin regimens and loose glycemic control rather than an indication of good glycemic management, as suggested by the high rates of hyperglycemia." (PMID 24499564, 2013). "Similarly, the absence of hyperglycemia is characteristic of multiple animal models of sepsis, and the data presented herein suggest that insulin sensitivity is preserved in endotoxemic mice in the absence of glucose supplementation." (PMID 23826335, 2013). "Treatment of male ZDF rats with CNX-011-67 for 7 weeks significantly enhanced insulin secretion in response to oral glucose load, delayed the onset of fasting hyperglycemia by 3 weeks, reduced nonfasting glucose excursions, fasting free fatty acids and triglyceride levels." (PMID 23692921, 2013). "Hyperglycemia may be attributed to enhancement of gluconeogenesis as a result of absence of insulin." (PMID 24364912, 2013). "No infants in this trial received insulin therapy for hyperglycemia." (PMID 23679669, 2013). "In our study, we have shown that the duration of hyperglycemia is a significant risk factor in the development of ROP, with each day of hyperglycemia increasing the risk by 7% in a population of ELBW infants who did not receive insulin therapy." (PMID 23679669, 2013). "Insulin treatment to normalize blood glucose levels failed to counteract the detrimental effect of hyperglycemia but could nevertheless restore the cardioprotective effects of ischemic preconditioning." (PMID 24371503, 2013). "To circumvent the confounding effect of the residual mild to moderate hyperglycaemia in these mice, we next examined the TAM-treated Glis3fl/fl/Pdx1CreERT+ mice early at 10 days after TAM administration, when the animals were still euglycaemic and had normal plasma insulin." (PMID 23197416, 2013). "Mild fasting hyperglycaemia (5.5–8.0 mmol/L) is present from birth, whilst insulin response, and therefore postprandial glucose levels, are normal such that most patients demonstrate only small glucose excursions after meals (<3.0 mmol/L following a 75 g oral glucose tolerance test)." (PMID 23766565, 2013). "Whether these are or not related with the anti-apoptotic effect of insulin in the absence of hyperglycemia, deserves further evaluation." (PMID 23497124, 2013). "Titration of basal insulin frequently does not take into account elevation of postdinner hyperglycaemia, so for a subset of patients, morning FPG may reflect a substantial fall from bedtime levels." (PMID 23061886, 2012). "Interestingly, CS treatment did not lead to obvious improvements in hyperglycemia or resistance to insulin, while in vitro MTT assays indicated that CS protects pancreatic beta cells against the toxic effects of STZ." (PMID 22474523, 2012). "The changes in both during hyperglycemia were different from the lack of increase during similar volume infusion (0.9% saline) with maintenance of euglycemia and thus cannot be attributed to volume or continued insulin infusion." (PMID 22701470, 2012). "These actions appear to be independent of insulin signaling, as shown in an in vitro model of induced gluconeogenesis, and may contribute to ameliorating hyperglycemia." (PMID 22905122, 2012).
Hyperglycemia (continued). "In addition, insulin therapy seems to reduce morbidity and mortality predominantly by preventing hyperglycemia rather than by a direct effect of insulin." (PMID 23031354, 2012). "At 10 weeks of age (the start of the study), ZDF rats already showed increased body weight, first signs of hyperglycemia (elevated blood glucose and HbA1c levels) and hyperlipidemia (FFA: 0.24±0.05 and 0.65±0.18 mmol/L for lean and ZDF, respectively; p<0.05), and increased serum insulin." (PMID 23071636, 2012). "Blood collected in the non-fasting state right before sacrifice revealed a hyperglycemia, a 6-fold increase in mean serum insulin concentration, a 2-fold increase in mean serum cholesterol concentration and a 70% increase in plasma HDL-cholesterol levels in the mice on the Western diet." (PMID 22394543, 2012). "However, diabetic patients' cells do not make use of glucose from the blood due to abnormal insulin metabolism, resulting in elevated blood glucose levels or hyperglycemia." (PMID 22611498, 2012). "Although our data and previous studies have shown that insulin benefits protein metabolism, the extent to which the benefit is derived from the correction of hyperglycemia as opposed to the direct effects of insulin remains unclear." (PMID 22480187, 2012). "Although these liver effects of FXR activation may prevent fasting hyperglycemia, it does not sufficiently explain the increased insulin sensitivity and glucose disposal in FXR agonist-treated mice as determined by glucose and insulin tolerance tests." (PMID 21991404, 2012). "There was no metabolic complication such as hyperglycemia or need for insulin." (PMID 22242614, 2012). "It was also suggested that treatment of hyperglycemia with exogenous insulin may not be supportive and may even be potentially detrimental in critically ill children." (PMID 21276273, 2011). "A strategy to differentiate the roles of hyperglycemia and insulin deficiency to diabetic complications is to separately restore insulin signaling in an affected tissue without effecting glucose exposure and to correct systemic hyperglycemia without increasing insulin levels." (PMID 22046295, 2011). "In contrast, in critically ill adult patients, hyperglycemia may persist for days to weeks with or without insulin therapy." (PMID 21276273, 2011). "Thus, the fasting hyperglycaemia in male mice under HFD and the elevated level of circulating insulin in mice under AD could have aggravated cardiac hypertrophy and alteration." (PMID 22166251, 2011). "Early phenomenon of T2DM is insulin insensitivity, which not only has negative metabolic consequences but also contributes subsequent pancreas β-cell exhaustion, resulting in the onset of clinical hyperglycemia." (PMID 21439094, 2011). "In ML mice treated with the antagonist GLP1 receptor exendin 9 (Ex9) hyperglycemia during OGTT was much significantly higher than in ML mice, thus suggesting that GLP1 signaling pathway is involved in glycemic response during OGTT, probably through modulation of insulin secretion." (PMID 21698161, 2011). "Activation of peripheral MOR may increase glucose utilization to ameliorate hyperglycemia under the absence of insulin should be considered." (PMID 19095661, 2011). "In addition macaques without overt hyperglycemia, but with impaired glucose clearance, impaired insulin secretion, and increased postprandial glucose concentrations, had a significant increase in HbA1c content to 3.5%." (PMID 21559266, 2011). "Insulin glargine may be expected to lower the blood glucose levels since it is a long-acting insulin; however, the duration of its action does not reach 24 hours with some recipients, which may be reflected by hyperglycemia." (PMID 21747829, 2011).
Hyperglycemia (continued). "Thus, the presented data show that neither decreased insulin sensitivity nor significantly decreased β-cell function after stimulation with hyperglycaemia or during challenge with arginine and GLP-1 explain the abnormalities in the glucose homeostasis in TS." (PMID 21406078, 2011). "It is also noteworthy that the control mice, even with severe hyperglycemia (∼400 mg/dL), did not secrete more insulin to reduce high blood glucose levels (4 wk after STZ, 0.48 ng/mL), indicating a very obvious deficit in insulin production and/or secretion in the control mice after STZ treatment." (PMID 21318185, 2010). "However, another study has shown that hyperinsulinaemia with concomitant hyperglycaemia at concentrations typically seen in insulin-resistant subjects does not affect plasma ghrelin but is decreased only at pharmacological insulin concentrations." (PMID 20700400, 2010). "However, the finding of hyperglycemia without changes in plasma insulin response after acute sleep disturbance makes this explanation less likely." (PMID 20339560, 2010). "Thus, we conclude that differences in hyperglycemia and the amount of insulin administered are not likely to account for the observed differences in histopathological development in these animals." (PMID 20806092, 2010). "However, chronic hyperglycemia has severe adverse effects on b-cell function, including glucose desensitization, b-cell exhaustion and finally a lack of insulin secretion and insulin storage." (PMID 21052542, 2010). "Therefore, any anti-inflammatory effects of the drug were not secondary to its action on insulin secretion or hyperglycemia." (PMID 21042558, 2010). "First, the definitions of secondary failure were different: in the UKPDS, failure was defined as patients who needed additional therapy, regardless of type, to control hyperglycemia, while the second study defined failure solely in terms of progression to insulin therapy." (PMID 20936101, 2010). "In these experiments, diabetic rats were not in ketoacidosis, and since they did not receive insulin, hyperglycemia could induce brain damage." (PMID 19812703, 2009). "However, at least two points must be considered: first, CoPP treatment did not significantly decrease the severity of hyperglycemia in our animal model and did not affect serum insulin levels; second, in contrast, circulating adiponectin levels were increased." (PMID 19038792, 2009). "In addition, to our knowledge no studies in humans have investigated separate hyperglycaemia without hyperinsulinaemia, as experimental glucose infusion will induce rapid production of insulin." (PMID 18290856, 2008). "Thus from the measurements of blood glucoseprofiles, a rate of the insulin supply by an insulin pump is adjusted so thatit can lead to neither conditions of hyperglycemia nor hypoglycemia." (PMID 18566688, 2008). "Thus, the decision to delay insulin and instead add a third OAD may prolong the state of toxic hyperglycemia." (PMID 18279520, 2008). "Treatment with conventional human insulin mixtures, however, may result in a non-physiological blood glucose response to a meal with high PPBG excursions, an extended period of hyperglycaemia and the risk of hypoglycaemia later in the day." (PMID 18657196, 2008). "The relation between hyperglycemia and outcome could be one of the explanations for the lack of benefit of trials using insulin in combination with glucose-potassium, i.e. GIK." (PMID 17284309, 2007). "The clinical value of this initial glucose infusion is not known and would depend on whether IIT works by reducing hyperglycaemia or through another action of insulin, which may be anti-inflammatory, anti-coagulant, or anabolic." (PMID 17623086, 2007). "Recombinant omentin enhances insulin-stimulated glucose uptake in adipocytes but so far it was not analyzed whether systemic omentin is affected by acute hyperglycemia." (PMID 17311679, 2007).
Hyperglycemia (continued). "The benefits of intensive insulin therapy may not solely be attributed to lowering hyperglycaemia, but may be mediated by the effect of insulin on protein and lipid metabolism, independent of its effects on glucose metabolism." (PMID 15566589, 2004). "However, this same unopposed glucagon effect can also contribute to delayed postprandial hyperglycemia, particularly after larger protein loads or mixed meals, due to increased hepatic gluconeogenesis occurring in the absence of dynamic insulin secretion/delivery." (PMID 41602572, 2026). "A subtle form of hyperglycemia was also noticed in a different cohort of non-diabetic UM patients compared to the age-matched controls, with a slight but significant increase in the fasting blood glucose levels together with an insulin-resistant serum profile in the former group." (PMID 41328998, 2025). "Animals were divided into three groups: in group 1 (n=15) rapid-acting insulin at a dose of 30 U was injected intraperitoneally, in group 2 (n=15) insulin was combined with sorafenib (per os 200 mg), and in the control group (n=15) no treatment of hyperglycemia was performed." (PMID 41169477, 2025). "However, clinicians may be less inclined to start an insulin infusion in patients without significant hyperglycemia, especially if EuDKA is not considered early in the differential." (PMID 40376133, 2025). "Existing studies have shown that dipeptidyl peptidase-4 inhibitors (DPP4is) reduce insulin requirements and hypoglycemia events compared to insulin, and therefore may be appropriate for glycemic management of select patients with mild hyperglycemia hospitalized for noncritical conditions." (PMID 39816910, 2025). "Given that increased glucagon secretion during DKA contributes to metabolic deterioration alongside insulin deficiency, therapeutic strategies targeting hyperglucagonemia—rather than focusing solely on hyperglycemia and insulin replacement—may offer additional clinical benefit." (PMID 41149695, 2025). "Additionally, residual confounding may persist despite multivariable adjustment, and we lacked detailed data on specific interventions (e.g., insulin therapy protocols, duration of hyperglycemia) that could influence outcomes." (PMID 41366962, 2025). "In addition, insulin may promote malignant transformation, cancer progression and metastasis through binding and activation of the IGF-1 receptor, and hyperglycaemia itself may increase cellular sensitivity to IGF-1, further contributing to cancer development and progression." (PMID 40357210, 2025). "Finally, the large increase in TXNIP by hyperglycemia may be limited by insulin, which acts as part of a negative feedback loop." (PMID 40559375, 2025). "Finally, while hyperglycemia at diagnosis may transiently affect lipid levels, the persistence of higher LDL-C in females—despite comparable glycemic control and basal insulin dosing—suggests that additional sex-specific mechanisms may be contributing to this risk." (PMID 41262843, 2025). "The somewhat lower rates of hyperglycemia and combined dysglycemia and higher rates of hypoglycemia in our study might be explained by older PMA at registration as well as by a developmental mechanism of decreasing insulin resistance and thus decreasing glucose concentrations." (PMID 40576801, 2025). "Notably, prior work in the T1DEXI dataset showed that PA undertaken with insulin on board in the preceding 4 h was more likely to reverse hyperglycaemia, highlighting a potential synergistic effect between recent insulin administration and PA when ketosis is absent." (PMID 41059660, 2025). "These non-ketotic hyperglycemia-related seizures may be refractory to traditional antiseizure therapy, yet they tend to resolve rapidly following correction of hyperglycemia with rehydration and insulin therapy." (PMID 41300233, 2025). "Thus, increased insulin secretion is unlikely to explain the sustained remission of hyperglycemia." (PMID 40371641, 2025).
Hyperglycemia (continued). "Although the results did not demonstrate the significant effect of bilberry extract application on serum insulin levels, significant effects on non-fasting hyperglycemia, which might be, at least partially, mediated by an increase in glucose uptake, were found." (PMID 40724509, 2025). "However, while the transition back to IV insulin drip was likely due to hyperglycemia, there are potentially other reasons a patient may have transitioned back to IV insulin that could not be specified given this study’s limitations." (PMID 39590191, 2024). "Interestingly, we observe increased neonatal lethality in heterozygous and homozygous Kcnk16 L114P mice in the C57BL/6J (B6) and the B6;CD-1 (ICR) mixed genetic backgrounds, respectively, likely due to severe hyperglycemia and lack of glucose-stimulated insulin secretion." (PMID 38700926, 2024). "However, a recent study found that only 3.5% of the dogs identified with random hyperglycemia between 126 and 200 mg/dL needed insulin treatment somewhere in the future, and none of those cases were in diestrus or pregnant at the time hyperglycemia was first documented." (PMID 38539988, 2024). "Inaddition, CGM glycemic trends may allow for proactive dose changes to try to preempthypoglycemia (or hyperglycemia) since any dose change with a weekly insulin might notmanifest itself for a few weeks, unlike with a daily basal insulin when the change ismanifest within the next 24 hours." (PMID 38224978, 2024). "Furthermore, we have shown that these DN-like defects, to be more precise, DSN-like defects, are independent of hyperglycemia and are rather dependent on the increase of insulin resistance specifically in sensory neurons by using UCHL1 transgenic flies and high-sucrose feeding." (PMID 38212312, 2024). "The action of insulin after binding to the insulin receptor on the cell surface (e.g. glucose uptake in skeletal muscle, inhibition of glycogenolysis and gluconeogenesis) is mediated by the intracellular PI3K pathway, and thus PI3K inhibition may lead to hyperinsulinemic hyperglycemia." (PMID 39437820, 2024). "In particular, the ability of BDNF to improve insulin sensitivity and influence energy expenditure suggests that it could help mitigate the effects of postprandial hyperglycemia and contribute to the lack of ketosis during fasting periods in bottlenose dolphins." (PMID 39199870, 2024). "If hyperglycemia persists despite the use of metformin, it may be appropriate to incorporate sodium-glucose cotransporter-2 (SGLT2) inhibitors into the treatment regimen, or other potentially effective pharmacologic options such as sulfonylureas or insulin should be considered." (PMID 39099917, 2024). "We hypothesized that general anesthesia with a volatile agent would suppress basal insulin secretion without altering hepatic insulin extraction, and that surgical stress would promote hyperglycemia through gluconeogenesis, lipid oxidation, and insulin resistance." (PMID 36808704, 2023). "Insulin is the principal hormone responsible for preventing hyperglycemia, raising the question of whether PDE4 inhibition may elevate blood glucose levels by lowering serum insulin levels (e.g., reducing insulin release) or reducing the sensitivity of metabolic/peripheral tissues to insulin." (PMID 36834669, 2023). "It shows that insulin, but not hyperglycemia, might be an important factor in renal UA handling, which should be taken into further consideration mainly when considering the effects of another cited study in which clamped euglycemia was achieved by insulin administration as it may alter the results." (PMID 37504524, 2023). "Since the skeletal muscles are quite permeable to glucose and play a role in whole-body insulin-mediated glucose uptake, whether the administration of EPE to STZ mice will result in facilitated glucose entry into skeletal muscle and reduced hyperglycemia is an interesting question." (PMID 37850072, 2023).